LOXL2 (lysyl oxidase like 2)
Diseases named in the same sentence as LOXL2 in open-access papers (continued):
Sharing a sentence is not in itself a finding about the gene and the disease.
breast carcinoma (continued). "To investigate the relationships between LOXL2, PEAR1, and PEAR1 Ser891 phosphorylation and CD44 in breast cancer, we subjected human TNBC samples to IHC." (PMID 39145451, 2024). "The degree of LOXL2-mediated H3 oxidation at lysine 4 (H3K4ox) is significantly greater in TNBC MDA-MB-231 cells and patient-derived xenograft tumours than in other breast cancer subtypes." (PMID 39247609, 2024). "In breast cancer, not only is high expression of LOX related to bone metastasis, LOXL2 has also been shown to promote lung metastasis of breast cancer." (PMID 37767404, 2023). "Some of the alterations identified are drivers of different tumors and for VM formation: S1PR1 (breast cancer), PDGFRB, TIE-1 (melanoma), LOXL2 (hepatocellular carcinoma) and interestingly TCF-4." (PMID 36797281, 2023). "A separate study also identified that similarly in breast cancer, OSM induces LOXL2 expression, subsequent collagen fiber alignment, and metastasis in vivo." (PMID 37841259, 2023). "In contrast, systemic administration of LOXL2 neutralizing antibodies disrupted fibrillar collagen deposition and fiber linearity in established MDA-MB-231 breast cancer xenografts." (PMID 35804902, 2022). "A further four more proteins, namely, TGFβ1, DAG1, LGALSBP3, and LOXL2, were found to be common between DCIS and breast cancer (all grades)." (PMID 36010848, 2022). "Another antibody that targets the active site of LOXL2, GS341, inhibits the development of tumors from MDA-MB-231 breast cancer cells, and inhibits their metastatic spread to lungs, but has not yet evaluated in clinical trials." (PMID 35682926, 2022). "Accordingly, cytoplasmic and perinuclear LOXL2 was found in human laryngeal squamous cell carcinomas (LSCC) and human breast carcinoma cells, and this expression pattern correlated with malignant progression and increased metastasis." (PMID 36232685, 2022). "LOXL2 overexpression is observed in many human cancers, including gastric cancer, hepatocellular carcinoma (HCC), breast cancer, and squamous cell carcinomas, and closely associated with their clinical-pathological characteristics and prognosis." (PMID 34836938, 2021). "Using an exploratory cohort, we identified markers of collagen processing (LOXL2, PRO-C3, C6M, and C1M) that differed between those with breast cancer versus controls." (PMID 34426581, 2021). "Specifically, LOXL2 was compared against OSMR expression in glioblastoma, breast cancer, prostate cancer, and ovarian cancer." (PMID 34011405, 2021). "For example, in hepatocarcinoma and breast cancer cells, the JNK pathway upregulates the lysil oxidase-2 (LOXL-2), which oxidizes Snail, preventing its phosphorylation by GSK-3β." (PMID 33800291, 2021). "We find that LOXL2 and H3K4ox are higher in triple-negative breast cancer (TNBC) cell lines and patient-derived xenografts (PDXs) than those from other breast cancer subtypes." (PMID 31462706, 2020). "Inhibiting LOXL2 activity shows a 55–75% decrease in primary tumor volume in female athymic nude mice, which were implanted with MDA-MB-231 human breast cancer cells." (PMID 32139696, 2020). "Pharmacological inhibition of LOX/LOXL2 abrogated the ECM network of CAF and significantly impeded tumor cell migration, like recent findings of CAF-LOXL2 function in breast cancer xenografts and human gastric cancer cell lines." (PMID 31061140, 2019). "In breast cancer cells, endogenous LOX and LOXL2 expression has been shown to be upregulated when the cells were incubated with fibroblast-conditioned medium or plated on a fibroblast-conditioned collagen matrix." (PMID 30701028, 2018). "Recently, a link between LOXL2 and RAMP3 expression has been found in many different cancer cell lines including MDA-MB-231, a metastatic breast cancer cell line." (PMID 28845385, 2017). "The efficacy of the LOXL2 inhibitors was tested in vitro in proliferation, migration and invasion assays in the MDA-MB-231 triple negative human breast cancer model." (PMID 28199967, 2017).
breast carcinoma (continued). "In breast cancer, LOXL4, LOX, and LOXL2, which are expressed in a hypoxia-inducible factor 1-dependent manner, recruit bone marrow-derived cells and facilitate colonization of the lungs." (PMID 28060764, 2017). "In fact, HIF-1α can overexpress and secrete lysyl oxidase (LOX), lysyl oxidase-like 2 (LOXL2) and LOXL4 in hypoxic breast cancer cells." (PMID 29099748, 2017). "Many individual markers such as stem cell marker Bmi-1, lysyl oxidase-like 2 (LOXL2), FOXC1, α9β1 integrin, and monocarboxylate transporter 1 were studied to find specific markers for basal-like breast carcinoma." (PMID 25510449, 2014). "Lysyl oxidase-like 2 (LOXL2) is a matrix-remodeling enzyme that has been shown to play a key role in invasion and metastasis of breast carcinoma cells." (PMID 23971878, 2013). "Moreover, LOXL2 can promote the invasion and metastasis of cancer cells by inducing EMT in colorectal cancer, breast cancer and liver cancer." (PMID 41281746, 2025). "In addition, LOXL2 is an independent prognostic factor for overall survival (OS) and metastasis-free survival (MFS) in breast cancer (hazard ratio of 2.27 and 2.10, respectively)." (PMID 33669630, 2021). "There is a major need for novel ways to treat and prevent breast cancer metastasis, and the mechanism behind OSM’s induction of LOXL2 could prove to be exploitable in the race for more effective cancer therapies." (PMID 34011405, 2021). "eHSP90α interacts with lysyl oxidase-like 2 (LOXL2) and allows the latter to assume its functional conformation favoring the migration of breast cancer cells and with tissue plasminogen activator (tPA), favoring the conversion of plasminogen in plasmin, a process that favors cancer invasion." (PMID 34360868, 2021). "We generated murine 4T1 breast cancer cells that stably overexpressed LOX and LOXL2, respectively, using a lentiviral delivery system to test whether lysyl oxidases indeed conferred a chemoprotective modification of the tumor ECM." (PMID 29780168, 2018). "Besides the MMPs, the enzymes such as LOXL2, LOXL4, procollagen lysyl hydroxylase-2, and heparanase also regulate breast cancer progression." (PMID 29983921, 2018). "Highly invasive breast cancer cells instead of non-metastatic cells present obviously high expression of LOXL2." (PMID 29728125, 2018). "LOXL2 has similar biological activities in ECM remodeling as LOX, and its overexpression indicates poor prognosis in patients with colon and esophageal squamous cell carcinoma, as well as gastric cancer and breast cancer." (PMID 29728125, 2018). "LOX-like protein 2 (LOXL2) is albeit non-traditional ECM cross-linking reagent in breast cancer metastasis to the lung." (PMID 29881724, 2018). "Although the expression of LOXL2 was determined to be lower than that determined in MDA-MB-231 cells, LOXL2-positive breast cancer cells, SW480 cells showed considerably higher migratory potential than LOXL2-negative cells, in migration assay and wound healing assay." (PMID 29113306, 2017). "LOXL2 even controls CDH1 by regulating H3K4me3 deamination, and LOXL2-E47 EMT factor plays a role in the repression of CDH1 in early metastasis colonization of breast cancer cells." (PMID 27285767, 2016). "More specifically, it has been shown that HIF-1α may induce an enhanced expression of lysyl oxidase (LOX), lysyl oxidase-like 2 (LOXL2) and LOXL4 in hypoxic breast cancer cells within primary breast tumour." (PMID 23301832, 2013). "We previously showed that LOXL2 expression is clinically correlated with increased metastasis and poor survival in breast cancer patients with estrogen receptor (ER)-negative tumors." (PMID 23971878, 2013). "LOXL2, a member of the lysyl oxidase (LOX) family, is overexpressed in multiple human malignancies including gastric cancer, hepatocellular carcinoma, breast cancer, and squamous cell carcinoma, where it correlates with aggressive clinicopathological features and poor prognosis." (PMID 41357999, 2025).
breast carcinoma (continued). "Collectively, these experiments provide clear evidence that Hsp90 does not activate proLOXL2 and Hsp90-proLOXL2 interaction, and subsequent activation to LOXL2 does not change the alignment of Collagen-1 fibers or the invasiveness of breast cancer cells through Collagen-1 fibers." (PMID 37958410, 2023). "For instance, Loxl2 genetic deletion in mammary epithelial cells had no impact on fibrillar collagen deposition or ECM biomechanical properties in the PyMT genetically engineered mouse model of breast cancer." (PMID 35804902, 2022). "In breast cancer, LOXL2 expression is negatively correlated with OS and metastasis-free survival (MFS) in patients with ER negative invasive breast cancer, whereas suppression of LOXL2 in mouse breast-cancer models impairs invasion and metastasis of breast cancer cells." (PMID 36293126, 2022). "Overall, we speculate that while the impact of LOXL3 inhibition may vary with breast cancer subtype, the specific therapeutical inhibition of both LOXL1 and LOXL2 but not of LOXL4 may be beneficial in breast cancer." (PMID 35800439, 2022). "Moreover, preclinically in mouse models the overexpression of LOXL2 by breast cancer cells significantly enhanced lymphangiogenesis and lymph node metastasis." (PMID 34833492, 2021). "As the human breast cancer patient data demonstrated a correlation between the proinflammatory cytokine OSM and the collagen crosslinking enzyme LOXL2, we set out to determine whether OSM could promote the expression of LOXL2 at the transcriptional level." (PMID 34011405, 2021). "As no LOXL2-specific inhibitors are currently available, we therefore tested whether reducing the levels of functional LOXL2 would increase the sensitivity of breast cancer cells to chemotherapy." (PMID 31462706, 2020). "An earlier study showed that LOXL2 overexpressing mice does not develop cancer, however, the application of carcinogen could promote cancer growth or metastasis in breast cancer models." (PMID 31569601, 2019). "Our data further show that the effects of LOXL2 activity inhibition on breast cancer cell proliferation and ultimately tumor progression are manifested through an interaction with the surrounding microenvironment, and not necessarily a direct tumor cell response to LOXL2 enzymatic inhibition." (PMID 28199967, 2017). "We speculate that while the impact of LOXL3 inhibition may vary with breast cancer subtype, the therapeutical inhibition of LOX, LOXL1 and LOXL2 but not of LOXL4 may be the most beneficial." (PMID 35800439, 2022). "Similarly, the hypoxia-induced lysyl oxidase like-2 protein (LOXL2) can promote EMT and endow breast cancer cells with the ability to switch from dormant non-CSCs into proliferating metastatic CSCs." (PMID 33193295, 2020). "This was in contrast with the expression of known HIF target genes involved in breast cancer metastasis not included in the hypoxia signatures (LOX, LOXL2, LOXL4, CCL2, L1CAM, ANGPT1, and ANGPT2), whose expression showed a positive correlation with the signatures." (PMID 29540773, 2018). "Similarly, it has been shown recently that in breast cancer the pro-metastatic function of LOXL2 is independent of its role for ECM remodelling, since neither Loxl2 ablation nor overexpression affected ECM stiffness or organisation in the metastatic and primary tumour sites." (PMID 29953488, 2018).
liver fibrosis (48 papers, 2013 to 2026). "As a member of the LOX family, LOXL2 dysregulation is linked to the pathogenesis of several diseases, such as liver fibrosis and heart failure." (PMID 34308761, 2021). "LOXL2 plays a critical role in collagen crosslinking during liver fibrosis development, with its inhibition linked with reduced liver fibrosis." (PMID 32296422, 2020). "Here, we studied the mode of action of a novel potent, cell-permeable LOXL2 inhibitor PAT-1251 on hepatic fibrosis." (PMID 41385725, 2026). "MSC-derived exosomal miR-27b-3p can attenuate liver fibrosis by downregulating the Yes-associated protein and lysyl oxidase-like 2 (YAP/LOXL2) pathway." (PMID 41310755, 2025). "Recent research indicated that MSC-sEVmiR−4465 effectively delivers miR-4465, reducing HSC activation and mitigating the progression of liver fibrosis by downregulating LOXL2." (PMID 40002806, 2025). "Lysyl oxidase-like 2 (LOXL2) mediates the crosslinking of extracellular collagen, reflecting qualitative changes in liver fibrosis." (PMID 38740815, 2024). "Inhibition of LOXL2 follows the onset of liver fibrosis and augments collagen degradation, which influences tissue stiffness and resilience." (PMID 38475870, 2024). "This study investigates the efficacy and underlying mechanisms of human umbilical cord-derived exosomes (MSC-ex) in LOXL2 inhibition of liver fibrosis." (PMID 37328872, 2023). "Previous studies found that expression of LOX, LOXL1, and LOXL2 are increased in patients with liver fibrosis." (PMID 36711017, 2023). "We found that systemic administration of MSC-ex significantly reduced LOXL2 expression and collagen crosslinking, delaying the progression of CCl4-induced liver fibrosis." (PMID 37328872, 2023). "The distinct role of LOXL2 in a wide range of diseases, including liver fibrosis, has been elaborated." (PMID 37328872, 2023). "For example, a study has shown that lysyl oxidase-like 2 (LOXL2) monoclonal antibodies can alleviate liver fibrosis and promote fibrosis reversal in mice." (PMID 37153080, 2023). "Recently, inhibition of LOXL2 by small-molecule inhibitors and monoclonal antibodies has decreased fibrosis and increased survival in rodent models of liver fibrosis." (PMID 37328872, 2023). "Recent studies suggest that targeting LOX, LOXL1, or LOXL2 is an attractive strategy for treating mouse liver fibrosis." (PMID 37328872, 2023). "In this study, we investigated the effects and molecular mechanisms of MSC-ex on LOXL2 modulation in carbon tetrachloride-induced liver fibrosis mouse models and in vitro cell culture systems." (PMID 37328872, 2023). "Therapeutic LOXL2 inhibition has been shown to suppress liver fibrosis progression and promote its reversal." (PMID 37328872, 2023). "It was strongly expressed in fibrotic liver in mice, moreover, inhibition of LOXL2 attenuates thioacetamide-induced hepatic fibrosis." (PMID 35093101, 2022). "In mouse models of mild liver fibrosis, it has been shown that inhibition of LOXL2 with a specific monoclonal antibody (AB0023) prevents fibrosis." (PMID 34337431, 2021). "Although LOXL2 has been widely studied in cancer and fibrotic diseases such as idiopathic pulmonary fibrosis, liver fibrosis, and cardiac fibrosis, its expression and function in AD were unclear." (PMID 34307505, 2021). "For example, simtuzumab, a humanized IgG4 anti-lysyl oxidase like 2 (LOXL2) monoclonal antibody was discontinued after a phase 2 clinical trial in NASH patients with liver fibrosis (clinicaltrials.gov—NCT01672879)." (PMID 34588551, 2021). "A later study showing rapid downregulation of LOXL2 after liver injury in contrast to stable upregulation of LOX and LOXL1, suggests a rather minor role of LOXL2 in liver fibrosis." (PMID 32260126, 2020). "Here we show in a carbon tetrachloride (CCl4)-induced liver fibrosis murine model that treatment with a novel anti-lysyl oxidase like 2 (LOXL2) neutralizing antibody, which targets extracellular LOXL2, significantly improves fibrosis resolution." (PMID 32296422, 2020).
liver fibrosis (continued). "In one study, the benefit of concurrent treatment with an allosteric anti-LOXL2 mAb (AB0023) in a reversible model of CCL4-induced liver fibrosis was assessed." (PMID 32296422, 2020). "Here, we have used advanced high-resolution SEM imaging to uncover the effects of LOXL2 inhibition on collagen assembly in situ in a different model of liver fibrosis." (PMID 32296422, 2020). "Studies trying to understand the biochemical changes affecting fibrosis irreversibility have pinpointed LOXL2 as a key fibrogenic enzyme in liver fibrosis of various etiologies." (PMID 32296422, 2020). "Overall, these results demonstrate that inhibition of LOXL2 using our novel active-site neutralizing mAb reduces the amount of fibrotic collagenous matrix in liver fibrosis and modifies its arrangement and assembly." (PMID 32296422, 2020). "We show here that inhibition of LOXL2 activity during progressive liver fibrosis leads to increased accumulation of MoMFs within the liver parenchyma, particularly in the vicinity (up to 15 μ) of fibrotic collagen fibrils." (PMID 32296422, 2020). "Here we show for the first time, using high-resolution imaging, that inhibition of LOXL2 under conditions of progressive liver fibrosis changes the spatial organization of the fibrotic fibers." (PMID 32296422, 2020). "Our results indicate reduced collagen packaging following treatment with GS341, suggesting indeed that LOXL2 is a key mediator of collagen remodeling during experimental liver fibrosis." (PMID 32296422, 2020). "In line with previous reports, LOXL2 was found to play a significant role in fibrosis, with mRNA upregulation during liver fibrosis." (PMID 30536539, 2019). "While the relationship of serum LOXL2 with the stage and progression of pulmonary fibrosis has been demonstrated, its relationship with liver fibrosis is still under evaluation." (PMID 30986934, 2019). "In human lung and liver fibrosis, LOXL2 is overexpressed and treatments with an inhibitory monoclonal antibody against LOXL2 were reported to be beneficial." (PMID 29953488, 2018). "Time course studies further revealed a strong association (r2 ≥ 0.52) between plasma markers of inflammation (TLR2 activators) and hepatic fibrosis markers (Col1A, Timp1, LoxL2)." (PMID 26761430, 2016). "LOXL2 is therefore an interesting target for the hepatic fibrosis treatment and numerous approaches to inhibit LOXL2 have been developed." (PMID 27999454, 2016). "Elevated levels of lysyl oxidase-like-2 (LOXL2) expression were found in patient samples from liver fibrosis and primary biliary cirrhosis; moreover it was found that the upregulation of LOXL2 is limited to the fibrotic areas." (PMID 27999454, 2016). "A recent study showed that lung fibrosis of mice induced by bleomycin, and liver fibrosis, was inhibited by administration of anti-Loxl2 monoclonal antibody." (PMID 23927729, 2013). "Recent studies have highlighted the therapeutic potential of LOXL2 inhibition in mouse models of liver fibrosis, suggesting that LOXL2 could be a promising target for treating hepatic fibrosis." (PMID 40002806, 2025). "We investigated whether serum LOXL2 levels correlated with various markers for liver fibrosis or tumor." (PMID 38740815, 2024). "Our results provide, for the first time, evidence that MSC-ex could serve as a novel agent for anti-LOXL2 inhibition in liver fibrosis." (PMID 37328872, 2023). "In the present study, we described a previously unknown role for MSC-ex in LOXL2 inhibition in the HSC of the CCl4-induced liver fibrosis mouse model." (PMID 37328872, 2023). "It is also unknown whether MSC-ex could regulate LOXL2 expression and collagen crosslinking to suppress the progression of liver fibrosis." (PMID 37328872, 2023). "In this content, anti-LOXL2 represents an attractive antifibrotic strategy for liver fibrosis." (PMID 37328872, 2023).